SNORD30 (small nucleolar RNA, C/D box 30)
Synonyms: U30; RNU30
Gene: Small nucleolar RNA gene on chromosome 11 (62,853,663 to 62,853,732, reverse strand). Ensembl gene ENSG00000277846.
Gene Ontology:
Biological process: RNA processing
Cellular component: nucleolus
Homologues: Orthologues: chimpanzee SNORD30 (100% identical), macaque SNORD30 (96% identical), mouse Gm22680 (87% identical), pig SNORD30 (87% identical), rabbit SNORD30 (87% identical), rat Snord30 (87% identical), dog SNORD30 (86% identical), tropical clawed frog SNORD30 (71% identical), zebrafish snord30 (67% identical). Paralogues in human: SNORD30 (80% identical).
Diseases named in the same sentence as SNORD30 in open-access papers:
SNORD30 is named in the same sentence as 6 diseases in open-access papers, as found by Europe PMC text mining. Sharing a sentence is not in itself a finding about the gene and the disease. The quoted sentences say what the papers report.
glioma (1 paper, 2017). A benign or malignant brain and spinal cord tumor that arises from glial cells (astrocytes, oligodendrocytes, ependymal cells). "For instance, U30 (SNORD30) was reported as up-regulated in pediatric gliomas and seems to correlate with the shorter time to progression in multiple myeloma." (PMID 28817650, 2017).
infection (1 paper, 2022). The state of being infected such as from the introduction of a foreign agent such as serum, vaccine, antigenic substance or organism. "The silencing of SNORA/Ds encoded within RPS11 (SNORD35B), SNHG3 (SNORA73A, SNORA73B), and SNHG1 (SNORD22, SNORD25, SNORD26, SNORD27, SNORD28, SNORD29, SNORD30, SNORD31) inhibited infection with influenza A virus." (PMID 36430145, 2022).
SNORD30 also shares sentences with these, for which no sentence is quoted: cancer (1 paper); malaria (1); multiple myeloma (1); peripheral T-cell Lymphoma (1).